ALB (albumin)
Diseases named in the same sentence as ALB in open-access papers (continued):
Sharing a sentence is not in itself a finding about the gene and the disease.
Sepsis (continued). "To date, no study has specifically investigated albumin as a marker for sepsis in dogs." (PMID 25430894, 2014). "Our results demonstrate that during the initial phases of sepsis renal damage occurs and it consists of structural and ultrastructural alterations of some renal corpuscles and diffuse alteration of the glycocalyx components of the GFB which leads to increased permeability to albumin." (PMID 22108136, 2011). "This may reflect continued development of AKI in patients without sepsis, or it may reflect delayed excretion of substances competing for tubular reabsorption with uCysC, such as albumin, or it may be unrelated." (PMID 20459852, 2010). "The set consisted of low arterial pH, low bicarbonate, low platelet count and high SOFA score, particularly in noncardiac (surgical) patients, and these predictors were independent of sepsis, interval until testing, intubation with etomidate, baseline cortisol and albumin levels." (PMID 17524133, 2007). "In addition, the SAFE study suggested that administering albumin, as compared to administering saline, to patients with severe sepsis did not worsen organ function and might have reduced the risk of death." (PMID 40649163, 2025). "We also hypothesized that a lack of SFA binding activity in the serum of patients with sepsis might be due to the saturation of prebound FA/lysoPL at the albumin–FA/lysoPL binding sites at which the bound FA/lysoPL were probably derived from the membranes of massive injured or dead cells." (PMID 39273360, 2024). "Our study showed that the concentration of albumin in blood tended to be lower in patients with KD combined with severe sepsis than in patients with KD combined with non-severe sepsis (P=0.082) and may reflect the significantly elevated levels of cytokines, such as IL-6." (PMID 37234775, 2023). "Moreover, the use of albumin as an add-on fluid therapy in sepsis may confer benefit in those with baseline hypo-albuminemia, although results of clinical trials on albumin indicated no benefit on mortality." (PMID 37728777, 2023). "However, a prespecified subgroup analysis of 28-day mortality showed a non-significant trend favoring albumin in severe sepsis and normal saline in trauma, with a post hoc analysis in the trauma subgroup suggesting higher mortality with albumin in patients with traumatic brain injury." (PMID 37764075, 2023). "Studies reported that ALB to PCT ratio could be used as a sensitive early marker of nosocomial bloodstream infection in patients with intracerebral hemorrhage and a higher PAR level is strongly correlated with higher mortality in patients with sepsis-induced acute kidney injury." (PMID 36908271, 2023). "The premorbid ambulation ability with the albumin level as an indicator of nutritional status and the C-reactive protein level as an inflammatory biomarker can be combined to predict 28-day mortality in elderly patients diagnosed with sepsis and is not inferior to the SOFA score." (PMID 35962331, 2022). "Consequently, the randomized controlled ALBIOS trial studied the impact of albumin administration in severe sepsis and septic shock, and although this also showed no mortality benefit, a post hoc subanalysis suggested that there was a lower 90-day mortality in the albumin group with septic shock." (PMID 32819439, 2020). "We conclude therefore that albumin therapy to replace bound albumin, or strategic addition of HSA to increase the overall concentration in the fluid components of delivery (plasma and interstitial fluid, etc.)might alleviate some of the symptoms leading to sepsis." (PMID 33088822, 2020). "Therefore, there are no data from studies on sepsis that could suggest a potential advantage of albumin infusion over normal saline during SBP." (PMID 30374936, 2018).
Sepsis (continued). "None of the postoperative observations (albumin infusion volume, the incidence of pneumonia and intestinal infection, serum potassium level, and blood glucose level) were significantly different between the sepsis-positive and sepsis-negative groups (P > 0.05)." (PMID 30026670, 2018). "Furthermore, albumin did not affect the concentrations of most hepatic cytokines measured in this study, further supporting that resuscitating with albumin does not have a significant effect on hepatic inflammation during early sepsis." (PMID 28105603, 2017). "However, as the value at 72 h was not significant, this demonstrated that the CRP/albumin ratio at 72 h may not be used as a tool to guide decisions on the treatment of patients with severe sepsis and septic shock." (PMID 26158725, 2015). "Significant association did not exist between BMI and serum albumin levels in patients with CABG postoperative complications such as deep sternal region infection, leg infection, cerebrovascular accident/ transient ischemic attack, low cardiac output, sepsis, or requiring ICU more than 3 days." (PMID 25031829, 2014). "Laboratory trends of PIICS criteria over time were compared between patients with and without sepsis regarding individually obtained results for ALC, albumin, and CRP." (PMID 40555121, 2025). "Unlike Sepsis, among patients diagnosed with ARF, regardless of hospital outcome (for both alive and dead patients), among SOFA score, Lactate Albumin Ratio, lactate alone, and albumin alone had a significant correlation (r2 < 0.1)." (PMID 40130722, 2025). "Clinical observations have shown that the lactate-to-albumin ratio (LAR) behaves differently depending on infection site, with variable predictive performance across disease contexts like sepsis with or without hepatic involvement." (PMID 41590227, 2025). "Red blood cell distribution width to albumin ratio (RAR) is a novel biomarker and its prognostic effect on critically ill patients with sepsis has not been extensively investigated." (PMID 41204545, 2025). "Conversely, a significant negative correlation was found between CRP levels and the ALB-CRP ratio (r = − 0.61), suggesting an inverse relationship in the context of sepsis progression." (PMID 38839818, 2024). "This study found that diabetic individuals with UTIs and sepsis had substantially higher levels of CRP and WBC and a lower level of ALB compared to those without sepsis." (PMID 38771840, 2024). "Significant differences were found in ALB, SAA and BLA levels, with the sepsis group showing higher values than the non-sepsis group (P < 0.05)." (PMID 39039452, 2024). "Based on these findings, we thought it would be appropriate to examine nutritional assessment and sepsis outcomes using the CONUT score, which includes cholesterol levels, rather than albumin carriers." (PMID 36832250, 2023). "In our study, we observed that albumin, glucose, and BUN were significant markers in the sepsis-negative group." (PMID 37626427, 2023). "Based on these, we thought it would be appropriate to examine nutritional assessment and sepsis outcomes using the CONUT score, which includes cholesterol levels, rather than albumin carriers." (PMID 36832250, 2023). "Lactate and platelet counts were significant in the positive group, while albumin, glucose, and BUN were significant in the sepsis-negative group." (PMID 37626427, 2023). "For patients with sepsis or ARDS and undergoing ECMO, the evidence for albumin therapy is not robust enough to allow for a general recommendation." (PMID 37218881, 2023). "Albumin, as a negative acute-phase protein (APP), has previously been used as a prognostic biomarker in various infections, such as sepsis." (PMID 36614820, 2022). "A total of 2,027 patients with sepsis and CHD were included in our study, with 405 in the albumin group and 1,622 in the non-albumin group." (PMID 36337861, 2022).
Sepsis (continued). "Although the proportion of patients with sepsis was not significantly higher in the validation cohort than in the derivation cohort, the patients had lower hemoglobin (STD = −0.351) and serum albumin levels (STD = −0.322)." (PMID 33671984, 2021). "Together, albumin-adjusted plasma-free thiols were significantly reduced in patients with AKI and patients with sepsis compared with patients without AKI and sepsis." (PMID 33207555, 2020). "It was observed that hemoglobin, albumin, and PDW were significantly decreased in the sepsis group than in the nonsepsis group." (PMID 31781655, 2019). "First, an analysis was conducted on sepsis patients without CKD, controlling for various factors such as age, sex, stroke, WBC, ALB, TBIL, Scr, CO2CP, Lac, cTnI, FIB, CRP, MAP, ABX < 1 h, 24-h fluid balance, SOFA score, infection site, CKD, DM, CHF, COPD, VAD, MV, and CRRT." (PMID 40703277, 2025). "Septic neonate had significantly lower levels of hemoglobin (median = 13, IQR = 11.6-15 in sepsis group vs. median = 14.9, IQR = 12-16.6 in non-sepsis group, p = 0.005) and serum albumin (median = 2.6, IQR = 2.3-3.0 vs. median = 3.2, IQR = 2.8-3.5, respectively, p = 0.002)." (PMID 35669402, 2022). "Compared with neonatal pneumonia, our data revealed that neonates with sepsis had a higher CRP level and a lower ALB level, indicating that CRP and ALB may have the power in identifying sepsis from nonseptic neonates with pneumonia." (PMID 35873709, 2022). "A retrospective analysis was conducted on the oxidation forms of human albumin [human mercapto-albumin (HMA), human non-mercapto-albumin form 1 (HNA1) and human non-mercapto-albumin form 2 (HNA2)] in 60 patients with severe sepsis or septic shock and 21 healthy controls." (PMID 34447316, 2021). "Furthermore, we found a statistically significant positive correlation between HDL-C and albumin only in the sepsis cohort, but not in ICU patients without sepsis." (PMID 33195328, 2020). "Unfortunately, we did not have data on serum and urinary albumin/creatinine or serum corticosterone and ACTH concentrations that may be useful to identify renal or adrenal dysfunction in an animal model of sepsis and in humans." (PMID 31506547, 2019). "In addition, albumin, glucose, and BUN were significant in the sepsis-negative group." (PMID 37626427, 2023). "Furthermore, albumin, glucose, and BUN were significant in the sepsis-negative group." (PMID 37626427, 2023). "However, among sepsis patients with acute kidney injury (AKI) undergoing continuous renal replacement therapy (CRRT), there has been no similar study on the correlation between ALB levels and mortality alone." (PMID 35109818, 2022).
Cirrhosis (863 papers, 1994 to 2026). A chronic disorder of the liver in which liver tissue becomes scarred and is partially replaced by regenerative nodules and fibrotic tissue resulting in loss of liver function. "A reduced model using the Akaike Information Criterion (AIC) identified age, male sex, cirrhosis, creatinine level, and albumin level before therapy as factors associated with overall mortality." (PMID 41310195, 2025). "In cases of cirrhosis, albumin infusion reduces the risk of circulatory dysfunction caused by paracentesis and lowers the risk of spontaneous bacterial peritonitis, which in turn decreases the incidence of hepatorenal syndrome." (PMID 40766965, 2025). "We found that reduced albumin level was associated with increased risk of all outcomes in cirrhosis due to MASH and viral hepatitis." (PMID 40591542, 2025). "As well, a tool that combines laboratory test results (i.e., low albumin levels, high bilirubin levels) and use of specific medications (i.e., beta-blocker, statin) was developed to help predict outpatients with cirrhosis at risk of HE." (PMID 39635997, 2025). "In this study, TSP-1, Galectin-3, and Cystatin-C were found to be independent risk factors for death in patients with cirrhosis, whereas Albumin and Prealbumin were protective." (PMID 40417691, 2025). "The transition from compensated cirrhosis to acute decompensation was independently associated with lower hemoglobin levels (OR = 0.662; 95% CI: 0.507–0.865; p = 0.002) and lower albumin levels (OR = 0.211; 95% CI: 0.067–0.667; p = 0.008)." (PMID 41200179, 2025). "This protein is predominantly synthesized in hepatocytes such that the plasma level of albumin is considered a biomarker of liver synthesis function and a higher risk of cirrhosis ascites." (PMID 40647574, 2025). "An albumin level < 3.05 g/dL is associated with the development of CHE in patients with Child–Pugh B cirrhosis." (PMID 40362419, 2025). "In our study, albumin was inversely associated with adverse liver-related outcomes in cirrhosis patients." (PMID 40591542, 2025). "Albumin is a protein synthesized by the liver, and its levels typically decrease in conditions associated with impaired liver function, such as cirrhosis, or in nephrotic syndrome, where albumin is lost through the urine." (PMID 40872713, 2025). "A multicenter study demonstrated that an albumin level < 3.2 g/dL was associated with low performance in the Stroop test among Japanese patients with cirrhosis." (PMID 40362419, 2025). "Risk factors for cirrhosis progression included low albumin, high bilirubin, platelet count, age, and presence of esophageal varices." (PMID 40165825, 2025). "The baseline laboratory results also showed significantly lower platelet counts and albumin levels in AIH or overlap AIH-PBC patients with cirrhosis, as well as in general cirrhotic patients from other causes." (PMID 38337781, 2024). "A decrease in effective serum albumin is also associated with an increase in proinflammatory cytokines, which in turn is linked to worsening decompensation of cirrhosis." (PMID 38551716, 2024). "Cirrhosis, evidence of portal hypertension, higher bilirubin, lower platelet count, lower albumin, and more advanced age, are risk factors for HCC development after DAA therapy." (PMID 38273255, 2024). "The presence of ascites, serum endocan, IL-6, NLR, creatinine, sodium, TB, and albumin was associated with OFs in cirrhosis." (PMID 39724169, 2024). "Our study adds to the literature and shows that higher albumin levels were associated with higher odds of AKIN resolution in hospitalized patients with cirrhosis." (PMID 39518516, 2024). "Since albumin is an oncotic plasma protein, albumin infusion allows movement of water into the intravascular space, aids with fluid resuscitation, and thereby contributes to resolving cirrhosis-induced hypovolemia (loss of extracellular fluid) seen in ascites." (PMID 38551716, 2024).
Cirrhosis (continued). "Zn deficiency is attributed to impaired absorption in the gastrointestinal tract associated with cirrhosis and increased urinary excretion due to the enhanced relative binding of amino acids and Zn as a consequence of low albumin levels." (PMID 39795551, 2024). "In patients with cirrhosis and upper GI bleeding, impaired liver function with high bilirubin and low albumin levels is associated with an increased mortality risk." (PMID 39272704, 2024). "This is because the hyper-oncotic nature of albumin has the potential to cause adverse effects in patients with decompensated cirrhosis." (PMID 38551716, 2024). "Terlipressin plus albumin was associated with greater improvement in renal function vs albumin alone in patients with cirrhosis and Hepatorenal Syndrome type 1." (PMID 39286706, 2024). "Previous studies have shown that albumin is associated with decreased mortality and improved patient outcomes among patients with cirrhosis and SBP." (PMID 38899040, 2024). "For example, the well‐known rs28929474:T allele in SERPINA1 is associated with higher albumin levels (implying lower disease risk), but at the same time, it is strongly associated with a higher risk of cirrhosis." (PMID 39425533, 2024). "Albumin levels of <4 g/dL can increase the risk of death 13.3-fold in patients with compensated cirrhosis, and levels of <3.5 g/dL are linked to rapid HIV progression." (PMID 38787212, 2024). "The authors suggested that higher blood levels of myostatin in patients with cirrhosis were associated with muscle loss, hyperammonemia, and impaired protein synthesis, which was reflected in low serum albumin concentration." (PMID 39590820, 2024). "The multifaceted contributions of albumin infusion in cirrhosis underline its potential in improving patient outcomes and addressing the challenges associated with cirrhosis management." (PMID 38551716, 2024). "Albumin is the first-line plasma expander for hospitalized patients with cirrhosis and AKI (European Association for the Study of the LiverEuropean Association for the Study of the Liver, 2018)." (PMID 39434907, 2024). "Pooled data presented in several meta-analyses show that BCAA supplementation significantly increases muscle mass and serum albumin and decreases hospital admissions and cirrhosis-associated complications such as HE and bacterial infections." (PMID 36765884, 2023). "All these properties are associated with the clinical effect of albumin and confirm its role as the first-choice plasma expander in patients with cirrhosis." (PMID 36769582, 2023). "Older age, male sex, presence of cirrhosis, lower platelet count, serum albumin level, and HBV DNA level were significantly associated with a higher risk of HCC." (PMID 37296898, 2023). "This study showed that patients with cirrhosis and HE who received albumin infusion had a higher risk score." (PMID 37770848, 2023). "In the present study, albumin levels were significantly associated with the risk of sarcopenia in patients with cirrhosis." (PMID 38071233, 2023). "There are particular changes to albumin's function and structure that are linked to diseases like cirrhosis in addition to decreased albumin production." (PMID 37525801, 2023). "Within the cirrhosis cohort, the only significant independent association with breakthrough infection was lower serum albumin concentration." (PMID 37870985, 2023). "Diseases, such as cirrhosis, are associated not only with reduced albumin synthesis but also specific alterations to its structure and function." (PMID 37111111, 2023). "An increased risk of pulmonary edema was observed in albumin studies of cirrhosis and bacterial infections unrelated to SBP, with a high Charlson comorbidity index, additional albumin dose, and pneumonia as possible risk factors." (PMID 38139434, 2023). "Oxidation of serum albumin in patients with cirrhosis and bacterial peritonitis causes decreased binding properties of albumin, predicting impaired transport function." (PMID 37926735, 2023).